SNAI2 (snail family transcriptional repressor 2)
Diseases named in the same sentence as SNAI2 in open-access papers (continued):
Sharing a sentence is not in itself a finding about the gene and the disease.
breast cancer (continued). "To test this hypothesis, we initially established an EMT model using an epithelial breast cancer cell line, MCF-7, and examined the effect of ELE on the TGF-β1-dependent signalling pathway and the nuclear transcription factors SNAI1, SNAI2, TWIST and SIP1." (PMID 23516540, 2013). "Three (5.2%) of the 59 women whose breast cancer expressed SNAI2 had the first distant cancer recurrence in the skin compared with 21 (12.9%) of the 163 women whose cancer did not express SNAI2 (P = 0.098)." (PMID 21914172, 2011). "In breast cancer cells, reduced expression of the circadian gene PER2 was found to correlate with increased expression of the pro-EMT genes Snail Family Transcriptional Repressor 2 (SLUG), Snail Family Transcriptional Repressor 1 (SNAI1), and Twist-related protein 1 (TWIST1)." (PMID 38173841, 2023). "A considerable amount of data sustains the involvement of FOXM1 in several features of breast cancer progression, such as the EMT, the migration and invasion abilities of tumor cells, in which FOXM1 controls the transcription of several metalloproteinases and the EMT inducer SNAI2." (PMID 31311575, 2019). "We hypothesised that microtubule disruption would inhibit TGF-β-induced expression of the breast cancer EMT-driving transcription factors Snail (SNAI1) and Slug (SNAI2) because a key mediator of their transcription, Smad2/3, is trafficked to the nucleus along microtubules." (PMID 31481735, 2019). "Similarly, we expanded the breast cancer input layer with the hyaluronan-mediated motility receptor (HMMR) connected to FN1; the TGFBR connected to SNAI1 and SNAI2; the interLeukin 1 receptor type I (IL1R1) and the thyroid hormone receptor beta (THRB) connected to TRAF1 and MYC, respectively." (PMID 28775339, 2017). "The basal-like/triple-negative breast cancer is a poorly differentiated and aggressive breast cancer subtype, characterized by the expression of a stem cell-like gene profile, by the cytoplasmic localization of beta-catenin and by CA9 and SNAI2 gene overexpression." (PMID 24260469, 2013). "High expression of both SNAI2 and PEAK1 did not predict OS probability among breast cancer patients reporting enrichments in either innate or adaptive immune cell content." (PMID 34239043, 2021). "In spite of the fact that in human breast cancer cells, NF-κB binds to the promoter regions of Snai2, Twist1, and ZEB2 and activates their transcription, PDGF-AB does not increase the expression of Snai2, Twist1, and ZEB2 in brain ECs." (PMID 32226439, 2020). "Moreover, we found that miR-33b does not alter the 3′UTR activity of the well-established EMT transcription factor SNAI2, suggesting that miR-33b regulates HMGA2, SALL4 and Twist1 in breast cancer cells without impacting EMT." (PMID 25919570, 2015).
melanoma (75 papers, 2011 to 2025). A malignant, usually aggressive tumor composed of atypical, neoplastic melanocytes. "Ectopic WT-Bmal1 and dHLH-Bmal1 increased genes associated with mesenchymal melanoma state, such as Sox9, Fn1, Col1a1, Prrx2, Klf4, Snai2, Twist2, Lmo1 and Axl31." (PMID 38245503, 2024). "SNAI2 has been directly implicated in melanoma progression by triggering the activation of the GSK-3β/β-catenin pathway." (PMID 37511550, 2023). "Interestingly, SNAI2 was previously linked to brain metastasis while activated STAT3 was shown to promote melanoma brain metastasis." (PMID 38635031, 2024). "Indeed, the loss of SNAI2/ZEB2 combined with the gain of ZEB1 is a factor involved in the poor prognosis of melanoma patients and is associated with resistance to MAPK-targeting and immune therapies." (PMID 38398085, 2024). "In melanoma, we previously showed that, during melanoma progression, a switch in the EMT-TFs’ expression occurs, with a loss of ZEB2 and SNAI2 expression and the upregulation of ZEB1 and TWIST1 expression." (PMID 38398085, 2024). "To this end, we overexpressed ZEB1, leading to a decrease in E-cadherin expression and an increase in N-cadherin expression, or silenced SNAI2 or ZEB2 in melanoma cells in 2D cultures." (PMID 38398085, 2024). "Interrupting the interaction between Pirin and BCL3 with a Pirin inhibitor has been shown to inhibit melanoma cell metastasis via suppression of snail homolog 2 (SNAI2)." (PMID 38033031, 2023). "For example, miR-33a-5p targets Snail family transcriptional repressor 2 (SNAI2) to suppress the migration of melanoma cells." (PMID 37432067, 2023). "In particular, Fra-1 (encoded by the gene FOSL1) is important for melanoma progression as its accumulation triggers the transcription factor switch that drives (partial)-EMT, downregulating Zeb2 and SNAI2 and directly upregulating Zeb1 at its promoter." (PMID 37181747, 2023). "Though SNAI1/Snail and SNAI2/Slug are considered to play the same biological role in EMT triggering in epithelial tumors, it has been shown for melanoma cells that SNAI2/Slug is responsible for melanocytic differentiation and thus suppresses EMT." (PMID 31921836, 2019). "For example TWIST1 and ZEB1 increase the metastatic potential of melanoma cells whereas SNAI2 (SLUG) and ZEB2 decrease it." (PMID 29432466, 2018). "A similar unexpected finding has recently been described in melanoma development suggesting that SNAI2's role in the pathogenesis of cancer goes beyond its well-known EMT regulation." (PMID 25686823, 2015). "It has been shown that pirin-BCL3 interaction is important for the regulation of SNAI2 expression and that the inhibition of this interaction resulted in the decreased migration of melanoma cells." (PMID 24390086, 2014). "Pirin is a transcriptional coactivator whose influence on NF-κB dependent transcription via interaction with BCL3 was shown in the case of SNAI2 expression in melanoma cells." (PMID 24390086, 2014). "Differential BMI1, TWIST1, and SNAI2 mRNA expression patterns correlate with malignancy type in a spectrum of common cutaneous malignancies, including basal cell carcinoma, squamous cell carcinoma, and melanoma." (PMID 40332096, 2025). "In addition, we analyzed the enrichment of transcription regulators with the 66 significant enhancers and found that several critical melanoma-associated TFs (e.g., SP1, SNAI2, HEXIM1, ASCL1) preferentially bind at these enhancer loci." (PMID 37904237, 2023). "The expressions of ZEB2 and SNAI2 fluctuated across the melanoma clusters." (PMID 35884783, 2022). "miR-33a is a well-known tumor suppressor downregulated in melanoma that targets snail family zinc finger 2 (SNAI2) and hypoxia inducible factor 1 (HIF-1) transcription factors positively regulating EMT and glycolysis, respectively, and tumor-promoting cyclin dependent kinase 16 (CDK16)." (PMID 34638331, 2021). "ZEB1 was also reported as one of the mediators of SNAI2-induced EMT in melanoma." (PMID 33095806, 2020).
melanoma (continued). "Furthermore, c-JUN expression was found to parallel with SNAI2 expression, and correlated with a mesenchymal gene signature in a panel of melanoma cell lines and a patient cohort." (PMID 27323831, 2016). "In addition, pirin controls melanoma cell migration through the transcriptional regulation of snail homolog 2 (SNAI2)." (PMID 22339359, 2012). "The results showed that SNAI2 was a powerful prognostic biomarker in urological tumors and can effectively predict the response to anti-PD-L1 immunotherapy, and consistent results were discovered in melanoma patients treated with anti-PD-1 and anti-CTLA4 therapy." (PMID 37251370, 2023). "The absence of SNAI2 is associated with the level of malignancy in melanoma." (PMID 36726781, 2022). "However, SNAI2 was recently reported to be co-expressed with MITF during melanoma progression." (PMID 25593989, 2014). "The DepMap survey also found significant direct relationships between SNAI1 and ZEB1 as well as SNAI2 and ZEB2 in melanoma cell lines, further supporting a potential role for snail and ZEB transcription factors in the CoREST-mediated phenotype switch." (PMID 38300709, 2024). "We observed a significant decrease in SNAI2 mRNA expression correlated with an increase in ZEB1 mRNA and protein expression along with melanoma progression towards an invasive state." (PMID 38398085, 2024). "We collected samples from mitf::Xmrk/+ medaka and compared SNAI2, ZEB1, and Tspan8 expression in normal skin, primary melanomas, and melanoma local metastases." (PMID 38398085, 2024). "When miR-22-3p is overexpressed in WM-266-4 melanoma cells, the cell viability is decreased, the expression levels of LGALS1, VIM, and SNAI2 are decreased, the expression level of CDH1 is increased, and cell apoptosis is increased." (PMID 39684214, 2024). "We further analyzed the expression level of SNAI2 and response to anti-PD-L1 immunotherapy in urological tumors, and anti-PD1 and anti-CTLA4 in melanomas." (PMID 37251370, 2023). "Previous studies reported that compared with NMM, the expression levels of SNAI2, MMP2, MIF, and AP1S2 were up-regulated in MM and were crucial roles in the metastasis and malignant progression of melanoma." (PMID 37880239, 2023). "Follow-up experiments suggested that ZEB2 and SNAI2 act as tumour suppressors but ZEB1 and TWIST1 facilitate BRAF signalling in melanoma transformation by downregulating MITF." (PMID 35740696, 2022). "An overlap in key regulators and stabilizers for hybrid E/M phenotypes and melanoma phenotypes (such as ZEB1, NFATC2, CDH1, SNAI2, NRF2) suggest common regulatory links." (PMID 36003764, 2022). "CDR1as was epigenetically silenced, and that led to the activation of IGF2BP and upregulation of its targets, such as SNAI2 and MEF2C, which contributed to melanoma metastasis." (PMID 35740696, 2022). "For instance, SNAI2, a stabilizer of the hybrid E/M phenotype, is a key regulator of the NCSC phenotype and metastasis in melanoma, suggesting its involvement in regulating the intermediate phenotypes in melanoma as well." (PMID 36003764, 2022). "For example, ZEB1 promotes the initiation and metastatic progression of melanoma which is supported by TWIST1, whilst ZEB2, supported by SNAI2, acts as a melanoma tumour suppressor." (PMID 35278142, 2022). "SLUG (SNAI2), a member of the Snail family, is upregulated in metastatic breast cancer, colon cancer, lung cancer, mesothelioma, and melanoma." (PMID 34809669, 2021). "After 24-h GH treatment, SK-MEL-30 human melanoma cells showed a modest but significant increase of multiple EMT-related genes including mesenchymal markers ZEB-1, SNAI1, CLDN1 and SNAI2, while the epithelial marker CDH1 was significantly downregulated." (PMID 33291663, 2020). "We found that silencing the SNAI2 and ZEB2 transcription factors, which behave as tumor suppressors in melanoma cells, significantly induced Tspan8’s endogenous expression at both the mRNA and protein levels in different melanoma cell lines." (PMID 38398085, 2024).
melanoma (continued). "A total of 195 TFs were predicted to be under the regulation of these elements including major, already established transcriptional dependency of melanoma (SOX10 and MITF) or factors like SNAI1 and SNAI2 that drive the transition toward the mesenchymal phenotype." (PMID 37408506, 2023). "Finally, the expression levels of SNAI2, MMP2, MIF, and AP1S2 were elevated in melanoma cells of MM, consistent with the results of previous studies." (PMID 37880239, 2023). "Furthermore, SNAI2-knockdown was also reported to suppress the activation of the PI3K/Akt/mTOR pathway, thereby suppressing the development of melanoma." (PMID 35654777, 2022). "Indeed, we observed changes in important EMT markers and regulators such as ZEB1, CDH1 (E-Cadherin), CDH2 (N-Cadherin), SNAI2, and TGFß1 in the MITF-KO cells as well as in TCGA melanoma samples." (PMID 33438577, 2021). "Our study suggests that Snail (SNAI1) rather than Slug (SNAI2) plays a role during later stages of melanoma invasion and metastasis." (PMID 27172792, 2016). "SNAI2 has been reported to be a key player for epithelial-mesenchymal transition (EMT), which is a crucial phenomenon during invasion, metastasis of melanoma, by repressing E-cadherin transcription and stimulating fibronectin expression, and MITF directly activates the transcription level of SNAI2." (PMID 22046555, 2011). "Similarly, the inhibition of SNAI2 or ZEB2 expression by siRNA, which led to an increase in ZEB1 expression, resulted in a significant reduction in cell stiffness correlated with an increase in the aspect ratio of melanoma cells and a decrease in circularity." (PMID 38398085, 2024). "Moreover, in melanoma tumors of the Gide2019 cohort, clinical advantages and therapeutic responses to PD-L1 and anti-CTLA4 blocking therapy were greater in patients with low SNAI2 expression." (PMID 37251370, 2023). "Also noteworthy, EMT-TFs may have opposing roles in a particular tumor type, such as melanoma, where ZEB1 promotes EMT programs with the help of TWIST1, while ZEB2 in cooperation with SNAI2/SLUG are inhibitors." (PMID 36754910, 2023). "While SNAI2 was shown to be positively correlated with MITF, the expression of CDH1 did not correlate with the expression of SNAI2 in the TCGA melanoma tumors which is consistent with the published findings in melanoma and melanocyte samples, despite CDH1 being a canonical target of SNAI2." (PMID 33438577, 2021). "Transcripts of SLUG (Snail Family Transcriptional Repressor 2), which contains an evolutionally conserved 8-mer-binding site in its 3′UTR, has been identified as a direct miR-203 target, and a higher level of SLUG protein has been observed in malignant melanoma samples compared with benign nevi." (PMID 30866509, 2019). "We also noticed that transcriptional regulators of EMT including SNAI1, SNAI2, and RUNX2 were present in this list, supporting the hypothesis that the phenotypical plasticity gained through this transdifferentiation process concurs with melanoma aggressiveness." (PMID 37408506, 2023).
ovarian carcinoma (63 papers, 2010 to 2025). A malignant neoplasm originating from the surface ovarian epithelium. "This study is aimed to conduct a meta-analysis to evaluate the prognostic value of lymphovascular space invasion(LVSI) and to explore the potential association of SNAI1 and SNAI2 with LVSI in ovarian cancer." (PMID 28039463, 2017). "The associations between SNAI2 expression level and variant clinicopathological characteristics of ovarian cancer patients were analysed with χ2 test (Fisher’s exact test)." (PMID 29041931, 2017). "However, the potential mechanism underlying the regulation of SNAI2 in ovarian cancer is limited." (PMID 35220872, 2022). "Research has demonstrated strong expression of SNAI2 in ovarian cancer cells, directly linking this expression to the cells’ ability to survive, proliferate, invade, and spread." (PMID 39192972, 2024). "The promoter area of SLC7A11 is bound by SNAI2, and when SNAI2 is blocked, SLC7A11 expression is down-regulated, which causes ferroptosis in ovarian carcinoma cells." (PMID 39192972, 2024). "SNAI2 cloud promotes the invasion of ovarian cancer cells by upregulating MARCKS expression and through regulating ferroptosis." (PMID 37251370, 2023). "Recent studies have shown that miR-506 inhibits TGFβ-induced EMT by targeting SNAI2 and suppressing vimentin and N-cadherin expression in ovarian cancer." (PMID 37529006, 2022). "The existing data in this study not only demonstrated the anti-tumor effect of SNAI2 knockdown on ovarian cancer, but also illustrated the promotive effect of SNAI2 knockdown on ferroptosis." (PMID 35220872, 2022). "This study aims to explore the regulatory mechanism of SNAI2 in ovarian cancer, and to uncover its correlation with ferroptosis." (PMID 35220872, 2022). "Previous studies have found that SNAI2 is activated in ovarian cancer cells and has the potential to promote lymphovascular diffusion." (PMID 36438923, 2022). "Several genes have been confirmed to be closely related to the occurrence and progression of ovarian cancer, including SNAI2, VCAM1, BRCA1, MMP2, MECOM, MXS1, PARP1 and so on." (PMID 35090503, 2022). "SNAI2 was found to induce EMT in ovarian cancer through suppressing miR-222-3p transcription and upregulating PDCD10." (PMID 35227285, 2022). "Firstly, to identify the connection among SNAI2, ferroptosis and ovarian cancer, the expression level of SNAI2, SLC7A11 and GPX4 in human normal ovarian cell line IOSE-80 and multiple ovarian cancer cells were detected." (PMID 35220872, 2022). "In terms of ovarian cancer, SNAI2 was frequently activated in the tumor stroma, and has potential to promote lymphovascular spread of ovarian cancer." (PMID 35220872, 2022). "In conclusion, we disclosed that SNAI2 knockdown suppressed tumorigenesis and development of ovarian cancer by promoting ferroptosis." (PMID 35220872, 2022). "The goal of this study is to clarify the connection among SNAI2, ferroptosis and ovarian cancer, and to uncover the potential regulatory mechanism." (PMID 35220872, 2022). "In conclusion, this study disclosed that SNAI2 knockdown or erastin exhibited an anti-tumor activity in ovarian cancer by promoting ferroptosis, shedding new insights of the regulatory mechanism of SNAI2-mediated ferroptosis in ovarian cancer." (PMID 35220872, 2022). "Erastin exhibited an anti-tumor effect on mice suffering from ovarian cancer, which was partly weakened by SNAI2 overexpression." (PMID 35220872, 2022). "SNAI2 reprograms stromal fibroblasts, and this contributes to tumor proliferation and ovarian cancer progression." (PMID 34122521, 2021). "After siRNA-EPYC interference, the invasion and metastasis ability of ovarian cancer cells was weakened, while the expression of SNAI2 was down-regulated and the expression of CDH1 is increased." (PMID 34888227, 2021).